HIF1A (hypoxia inducible factor 1 subunit alpha)
Diseases named in the same sentence as HIF1A in open-access papers (continued):
Sharing a sentence is not in itself a finding about the gene and the disease.
tumor (continued). "In the era of genetic and molecular medicine, gene-editing technologies such as CRISPR-Cas9 aim to permanently eliminate the HIF-1α gene, thereby reducing tumor growth and enhancing T cell-mediated immunity." (PMID 40963621, 2025). "Our extensive analysis reinforces the tumour suppressor WWOX as a key modulator of cancer metabolism through direct physical interaction with HIF1α via its WW domain, inhibiting its transactivation potential and promoting its degradation." (PMID 41007296, 2025). "2-Methoxyestradiol (2-ME) induces destabilization of the HIF-1α protein, thereby inhibiting its transcriptional influence on tumor growth." (PMID 40136686, 2025). "HIF-1α exhibits widespread overexpression in EC tissues and positively correlates with tumor invasion depth, distant metastasis, and microvessel density." (PMID 40746896, 2025). "HIF-1α plays a vital role in promoting tumor survival and advancement, and its levels are elevated in over half of primary human cancers and their metastases." (PMID 40362444, 2025). "Adaptation to oxygen fluctuations is critical for tumor progression, and hypoxia-inducible factor-1α (HIF-1α) serves as a key transcription factor mediating cellular responses to hypoxia." (PMID 41256331, 2025). "Given the central role of HIF-1α in metabolic reprogramming and tumor progression, it has emerged as a promising therapeutic target in CRC." (PMID 41008845, 2025). "It further drives tumor growth and reduces sorafenib sensitivity by upregulating HIF-1α and activating JAK2/STAT3 signaling." (PMID 41050691, 2025). "It was reported that RP11-390F4.3 is induced by hypoxia/HIF-1α and is involved in epithelial-mesenchymal transition and tumor metastasis." (PMID 40078531, 2025). "These myoCAFs drive resistance via TFE3‐mediated autophagy and PCYT1A‐led phosphatidylcholine overproduction, creating a phospholipid‐rich niche that activates tumor HSP90/HIF1A, promoting stemness and revealing actionable therapeutic targets for HSPC." (PMID 40917018, 2025). "Ascorbate therapy stimulates HIF hydroxylase activity, reducing HIF-1α levels and inhibiting tumor growth." (PMID 40301490, 2025). "The attenuation of HIF-1α expression can result in the downregulation of lipid metabolic pathways, consequently influencing tumor cell behavior." (PMID 41333208, 2025). "During the hypoxia process, the overexpression of hypoxia-inducible factor 1α (HIF-1α) (which is known to promote tumor cell growth) has been observed in different human cancers." (PMID 40872479, 2025). "Rapidly proliferating cancer cells within the tumor mass frequently create local hypoxic conditions, leading to the stabilization and activation of HIF‐1α." (PMID 41256732, 2025). "Specifically, WWOX expression is markedly reduced in poor-prognosis tumours (log2fc = −1.34), while HIF1A expression is elevated (log2fc = 1.09)." (PMID 41007296, 2025). "Studies have shown that under hypoxic conditions, tumor cells adapt to the low-oxygen environment by activating HIF-1α." (PMID 41019994, 2025). "Increased levels of HIF-1α stimulate the transcription of genes responsible for encoding VEGF and PDGF, promoting tumor development and progression." (PMID 40260303, 2025). "This technique allowed for more accurate and reliable observation of tumor dynamics and provided direct evidence supporting the regulatory relationship between L-2-HG and HIF1A." (PMID 41198650, 2025). "HIF-1α in tumor cells further inhibits the activity of α-KGDH, reduces the oxidation of α-ketoglutarate, and leads to the accumulation of succinate." (PMID 40557160, 2025). "Mechanistically, MAP17 overexpression leads to increased reactive oxygen species(ROS), which activates downstream effectors AKT and HIF-1α, enhancing the Warburg effect and promoting tumor growth." (PMID 39980550, 2025). "The WWOX/HIF1A expression ratio serves as a robust prognostic biomarker, reflecting the balance between tumour-suppressive and oncogenic pathways." (PMID 41007296, 2025).
tumor (continued). "In contrast to most tumor types, HIF1α in ccRCC is often diminished by chromosomal deletion and acts as a tumor suppressor, while HIF2α serves as the primary mediator of hypoxia signaling and the main driver of ccRCC biology." (PMID 40775208, 2025). "Experimental studies further confirm that increased HIF-1α expression promotes tumor growth, while HIF-1α suppression reduces it." (PMID 40143161, 2025). "Resveratrol, present in red grapes, inhibits HIF-1α and cytokine production, thereby decreasing tumor hypoxia and inflammation." (PMID 40136686, 2025). "Building upon the regulatory framework of HIF-1α under normoxia and hypoxia, it becomes essential to understand how this master transcription factor reprograms tumor biology." (PMID 41311849, 2025). "Inhibiting HIF-1α to target inflammation presents a promising strategy for enhancing treatment efficacy and decreasing tumor aggressiveness." (PMID 40136686, 2025). "HIF-1α plays key roles in cellular metabolism, angiogenesis, cell cycle progression, inflammation, immune regulation, and tumor development and metastasis." (PMID 41204699, 2025). "As a key signal transduction molecule activated under hypoxic conditions, HIF‐1α expression is generally elevated in tumours and performs crucial biological functions, including metastasis, in cancers." (PMID 40954549, 2025). "The impact of YFJDT on hypoxia‐inducible factor 1 alpha (HIF1A), ferroptosis, and vasculogenic mimicry (VM) is investigated using xenograft tumor models and A549 cells." (PMID 39912781, 2025). "HIF-1α not only promotes tumor cell proliferation and invasiveness but also enhances immune evasion by upregulating PD-L1." (PMID 39412136, 2025). "For instance, lactate can activate the Hypoxia-Inducible Factor-1α (HIF-1α) signaling pathway, boosting angiogenesis and tumor metastasis." (PMID 41164182, 2025). "MTA1 contributes to tumor angiogenesis by deacetylating HIF-1α and upregulating the production of histone deacetylase-1." (PMID 40660330, 2025). "TAMs enhance PD-L1 expression via tumor-derived factors such as IL-6, granulocyte-macrophage colony-stimulating factor (GM-CSF), and hypoxia-induced hypoxia-inducible factor 1α (HIF-1α) signaling." (PMID 40177538, 2025). "Results indicated that tumor patients presented with advanced cancer stage andlymph node involvement as well as poor differentiation when showing elevated HIF-1α expression (p=0.014, p=0.032, p=0.021)." (PMID 40636217, 2025). "These HIF-1α-mediated metabolic reprogramming events collectively enhance glycolytic flux and glucose-derived de novo serine biosynthesis, thereby promoting tumor cell proliferation." (PMID 40386781, 2025). "Another study highlights that competitive uptake of extracellular glutamine by clear cell renal carcinoma activates hypoxia-inducible factor 1α (HIF-1α) in tumor-infiltrating macrophages, inducing IL-23 secretion." (PMID 41041303, 2025). "Low Hb levels induce tumor hypoxia, activating HIF-1α to promote epithelial-mesenchymal transition (EMT)." (PMID 40969267, 2025). "Hypoxia inducible factor 1α (HIF-1α) is an important transcription factor in the hypoxic tumor microenvironment." (PMID 40709182, 2025). "Conversely, a low WWOX/HIF1A ratio corresponded to poor prognosis driven by heightened HIF1A activity and diminished tumour suppression." (PMID 41007296, 2025). "Another study found that resveratrol inhibits the growth of tumor cells under chronic stress via the HIF-1α axis and the β2-adrenergic receptor-2, which can contribute to tumorigenesis and cancer development." (PMID 40918466, 2025). "Tumor hypoxia induces stabilization of HIF-1α which, as mentioned, drives glycolysis and is hence responsible for the lactate production." (PMID 41235226, 2025).
tumor (continued). "Almost all solid tumors have a highly hypoxic microenvironment, and tumor cells highly express HIF-1α to maintain survival through glycolysis." (PMID 40563539, 2025). "Mechanistically, deferoxamine (DFO)-mediated HIF-1α inhibition blocks tumor growth and triggers apoptosis by inactivating the ROS/HIF-1α signaling axis." (PMID 40791591, 2025). "For example, HIF-1α is a critical transcription factor that is stabilized under hypoxia and is commonly found in tumor cores." (PMID 40759634, 2025). "HIF1α regulates genes involved in glucose metabolism, angiogenesis, and tumor cell survival under hypoxic conditions." (PMID 39859381, 2025). "The effect of HIF-1α in mediating the synergistic anti-tumor effects of these drugs was investigated, and anti-tumor actions were evaluated in vitro in A549 and H1299 NSCLC cell lines and in vivo in a mouse xenograft model." (PMID 41041327, 2025). "Simultaneously, YAP/TAZ can directly interact with HIF-1α or promote GLUT3 transcription to enhance tumor glycolysis." (PMID 41141851, 2025). "The excessive activation of HIF1α in cancer, despite oxygen availability, is often driven by oncogenes (e.g., ERBB2, PI3K, Ras, protein kinase B/AKT, mTOR) and mutations in tumour suppressors (e.g., Von Hippel–Lindau (VHL) and PTEN)." (PMID 41007296, 2025). "Synchronously, hypoxia-inducible factor 1α (HIF-1α), which is elevated in tumor-bearing conditions, collaborates with STAT3 to shift muscle metabolism from oxidative phosphorylation to glycolysis." (PMID 40704145, 2025). "This study characterizes a functional interaction between Estrogen-Related Receptor α (ERRα) and Hypoxia-Induced Factor α (HIF-1α) that enhances drug resistance and tumor aggressiveness under hypoxia." (PMID 40723264, 2025). "Once stabilized, HIF‐1α translocates to the nucleus, where it regulates a broad array of genes that affect various cellular processes, thereby promoting tumor survival, proliferation, and metastasis." (PMID 40227962, 2025). "For instance, increased mitochondrial ROS production can activate AMPK or stabilize HIF-1α, promoting angiogenesis, glycolysis, and resistance to apoptosis, traits that enhance tumor cell fitness in hypoxic environments." (PMID 40724998, 2025). "The resistance of tumor cells to ferroptosisdevelops when HIF-1α stimulates lactate production and enhances amino acid transporter activity, thereby supporting cancer cellsurvival in hypoxic environments." (PMID 40636217, 2025). "In HCC, cancer-associated fibroblasts (CAF) produce CCL5 that, upon binding to tumor cells, activates signals that interfere with the ubiquitination and degradation by the proteasome of hypoxia-inducible factor 1 alpha (HIF1α)." (PMID 41303618, 2025). "HIF1A mRNA levels are higher in IDH wild-type GBM than in those with an IDH mutation, confirming the characteristic metabolic profile of IDH mutant tumours, including reduced glycolysis." (PMID 41007296, 2025). "Among GEP-NET patients, it is observed that patients with an increased tumor expression of HIF-1α have a significantly lower median OS." (PMID 40565098, 2025). "Collectively, IH-induced HIF-1α stabilization, ROS accumulation, and β-adrenergic signaling foster DNA repair upregulation, drug efflux amplification, and tumor cell survival—directly compromising chemotherapy efficacy." (PMID 41357522, 2025). "Benserazide, an inhibitor of CBS, in combination with paclitaxel, decreased SIRT1 sulfhydration and hypoxia-inducible factor 1-alpha/vascular endothelial growth factor (HIF-1α/VEGF) expression in tumor models." (PMID 41465271, 2025). "HIF-1α signaling, as a typical response to hypoxia, is a key regulator under hypoxic conditions, increasing glycolysis and driving tumor development." (PMID 41298345, 2025). "Hypoxia modulation strategies, such as the use of oxygen carriers and vascular normalization agents, indirectly target HIF-1α activity by alleviating tumor hypoxia." (PMID 39981236, 2025).
tumor (continued). "Our discussion highlights that pseudohypoxia, induced by HIF-PH inhibitors, leads to an increase in HIF-1α levels in both immune and tumor cells under normoxic conditions." (PMID 40343532, 2025). "For instance, in pancreatic cancer models, pharmacological blockade of APE1’s redox activity by E3330 treatment decreased NF-κB, AP-1 and HIF1α signaling and induced marked tumor growth inhibition in vivo." (PMID 41446759, 2025). "Second, Reconstructing the Microenvironment Supporting TAM Survival: Tumor hypoxia drives TAM polarization toward the M2 phenotype primarily through activation of HIF-1α." (PMID 41472729, 2025). "A key aspect of tumor adaptation to the hypoxic environment and the promotion of malignant behaviors is the regulation of HIF-1α signaling pathways." (PMID 39781344, 2025). "Compared to HIF-1α, which plays a tumor-suppressing role in certain cases, HIF-2α is more prone to oncogenic effects, particularly in the regulation of lipid metabolism." (PMID 41451091, 2025). "Cancer cells are hypoxic and induce hypoxia-inducible factor-1α (HIF-1α), vascular endothelial growth factor expression, angiogenesis, and tumor growth." (PMID 39861907, 2025). "The depletion of HIF-1α elevates the expression of IFN-γ, activates NK cells, and enhances tumor infiltration, thereby highlighting the inhibitory effect of HIF-1α on NK cell activity." (PMID 40303301, 2025). "This study systematically reviews the molecular mechanisms by which NPs and TCM formulations inhibit VM formation across various tumor types, and summarizes multiple core intervention targets, including VE-cadherin, EphA2, MMPs, Twist1, HIF-1α, and PI3K/Akt." (PMID 41019994, 2025). "HIF-1α controls the expression of over 300 genes involved in key cellular processes, including the regulation of the genes that drive tumor growth." (PMID 40507913, 2025). "Meanwhile, the relationship between HIF-1α stabilization under normoxia and metabolic reprogramming of tumor cells is discussed, and future development in cancer is prospected." (PMID 39757165, 2025). "Under hypoxia-induced tumor microenvironment, activated HIF-1α promotes the expression of leucyl-tRNA synthetase 1 (LARS1) in exosomes derived from PC cells." (PMID 41019994, 2025). "In this discussion, we aim to integrate these findings, linking the differentially expressed genes to the broader context of the WWOX/HIF1A axis as a critical modulator of tumour aggressiveness and patient outcomes." (PMID 41007296, 2025). "Succinate secreted by tumor cells activates the PI3K/HIF-1α and ERK1/2 pathways via the SUCNR-1 receptor, thereby upregulating VEGF expression, inducing angiogenesis, and enhancing cancer cell migration." (PMID 41488637, 2025). "By activating the transcription of genes involved in glycolysis, angiogenesis, and cell survival, HIF1A orchestrates the adaptation of cancer cell metabolism to low oxygen environments, thereby promoting tumour progression and resistance to therapy." (PMID 41007296, 2025). "Our mass spectrometry, transcriptomic, and metabonomic analyses suggest that FGL1 regulates glycolysis by mediating the PI3K/AKT/HIF-1α pathway to influence malignant progression such as tumor proliferation and metastasis." (PMID 41024301, 2025). "HIF-1α and HIF-2α can be upregulated in normoxic conditions due to the loss of function of various tumor suppressors, independently of intratumoral hypoxia." (PMID 39470609, 2025). "These processes collectively enhance the transcriptional activity of HIF-1α, activating various genes that promote tumor survival." (PMID 40950984, 2025). "By activating genes involved in angiogenesis, invasion, metabolic reprogramming, and survival, HIF-1α contributes to tumor progression and metastasis." (PMID 40731797, 2025). "This suggests a potential therapeutic role for EZN-2968 in conditions where HIF-1α plays a critical role in tumor progression and survival." (PMID 39757165, 2025).
tumor (continued). "High GLUT3 expression is associated with tumor stemness, survival under nutrient-deprived conditions, and invasiveness, while GLUT1 upregulation is highly coupled to HIF-1α activation." (PMID 41463052, 2025). "Silver nanoparticles (AgNPs) influence HIF-1α levels, resulting in the promotion of autophagy in tumor cells." (PMID 40004215, 2025). "HIF-1α can regulate cell apoptosis and proliferation, enabling tumors to selectively multiply tumor clones that are more suitable for survival in anoxic microenvironments." (PMID 40420185, 2025). "Even in the presence of oxygen, NO can induce hypoxic responses by stabilizing HIF-1α, thus promoting hypoxia-driven metabolic adaptations in tumor cells." (PMID 41036604, 2025). "The dual role of HIF-1α—as a driver of tumor progression and a mediator of immune suppression—positions it as a central player in the interplay between cancer cells and their microenvironment." (PMID 39981236, 2025). "HEY1 is a canonical Notch target, and Notch–HIF1A crosstalk is well documented in hypoxic tumor microenvironments." (PMID 41238550, 2025). "Given its multifaceted role in tumor biology, HIF-1α represents an attractive target for therapeutic strategies aimed at enhancing immunotherapy outcomes." (PMID 39981236, 2025). "In malignant tumors, HIF-1α, in response to low oxygen levels, plays a critical role in multiple biological processes, including tumor cell migration and invasion, tumor angiogenesis, and immune evasion." (PMID 40936898, 2025). "Researchers have observed that administering the antioxidant NAC to mice bearing tumor xenografts decelerated tumor growth, which was attributed to reduced HIF-1α expression, demonstrating the critical role of ROS in driving cancer progression." (PMID 40563367, 2025). "Hypoxia and HIF-1α signaling are key components of tumor progression, as well as resistance to therapeutic interventions; the translation of these insights calls for more integration of hypoxia-targeted strategies into current clinical practice." (PMID 40507913, 2025). "In the hypoxic tumor microenvironment, HIF-1α promotes angiogenesis and tumor invasion and directly promotes OTUD6B transcription." (PMID 41050073, 2025). "In our study, we found that although PDT treatment alone did not result in a reduction in HIF-1α expression within the tumour, the combination treatment of PDT with TPZ significantly reduced HIF-1α expression within the tumour." (PMID 40149700, 2025). "Over time, these highly adapted tumor states often evolve to silence IFN-induced pathways while concurrently activating HIF1A-mediated hypoxia signaling." (PMID 40885189, 2025). "HIF-1α regulates the expression of several genes involved in tumor adaptation to hypoxia, including stromal cell-derived factor 1 (SDF-1α)." (PMID 40867316, 2025). "As previously discussed, mounting evidence indicates that HIF-1α facilitates tumor cell proliferation through various mechanisms." (PMID 41311849, 2025). "Its expression under cyclic and chronic hypoxia contributes to inflammation, tumor survival, and interacts with the HIF-1α and NF-κB signaling pathways, reinforcing its role in the stress-adaptive transcriptional network." (PMID 41193950, 2025). "The inhibition of HIF-1α has previously been shown to reduce tumor-induced immune suppression, and B+A combination therapy has the potential to reprogram the tumor microenvironment and facilitate anti-tumor immune responses." (PMID 41041327, 2025). "For example, by upregulating VEGF, HIF-1α promotes the formation of abnormal, leaky blood vessels that sustain tumor growth but also exacerbate hypoxia." (PMID 39981236, 2025). "Under hypoxic conditions, tumor cells accumulate lactate due to enhanced glycolysis, and HIF-1α lactylation stabilizes the protein by reducing its ubiquitination and proteasomal degradation." (PMID 41583433, 2025).